CGAS (cyclic GMP-AMP synthase)
Diseases named in the same sentence as CGAS in open-access papers (continued):
Sharing a sentence is not in itself a finding about the gene and the disease.
myocardial infarction (continued). "Extensive studies have revealed that the activation of cGAS-STING pathway is implicated in the pathophysiology of CVDs, including atherosclerosis, myocardial infarction (MI), ischemia-reperfusion (I/R) injury, myocarditis, cardiomyopathy, HF, and aortic aneurysm and dissection (AAD)." (PMID 40461989, 2025). "The cGAS-STING pathway has also been studied in myocardial infarction (MI)." (PMID 39861173, 2025). "The release of endogenous substances from myocardial cells during myocardial infarction will initiate the cGAS-STING signaling pathway to induce the generation of a good deal of inflammatory factors and inflammatory cells, and intensifies the necrosis of myocardial cells." (PMID 37781360, 2023). "Two independent groups investigated the relevance of cGAS-STING in myocardial infarction healing." (PMID 34381828, 2021). "During myocardial infarction (MI), the cGAS‐STING pathway hinders tissue repair through type I IFNs." (PMID 39158380, 2025). "cGAS is involved in important biological processes such as macular degeneration, cellular senescence, and myocardial infarction (MI), heart failure(HF), and cardiac hypertrophy." (PMID 38720328, 2024). "Not only limited to myocardial infarction, high expression of the cGAS–STING pathway in different causes of cardiac dysfunction has been shown to be involved in the development of cardiac dysfunction, and cardiac function is significantly protected when the cGAS–STING pathway can be inhibited." (PMID 34906241, 2021). "Thus, cGAS-dependent signalling may play a vital role in mtDNA-induced inflammatory responses after myocardial infarction." (PMID 29511093, 2018). "After deletion of cGAS or STING, myocardial function and the survival rate in myocardial infarction mice were both improved." (PMID 38525112, 2024). "cGAS-STING has been shown to sustain chronic inflammation in pathologic conditions such as obesity-induced diabetes, myocardial infarction, and chronic inflammatory diseases." (PMID 36127466, 2022). "The genetic or pharmacological disruption of cGAS-STING and type I IFN signaling improved survival and pathological remodeling in a myocardial infarction mouse model." (PMID 33633744, 2020). "In comparison to WT mice, the early survival rate of myocardial infarction mice lacking cGAS, STING, and IRF3 was significantly improved." (PMID 37781360, 2023). "In addition to the cGAS–STING pathway being shown to be activated in vitro, the cGAS–STING pathway was shown to exacerbate the pro-inflammatory response in a mouse model of myocardial infarction." (PMID 34906241, 2021). "Interestingly, patients suffering from the accelerated aging disease Hutchinson Gilford Progeria Syndrome (HGPS) often die from CVDs like myocardial infarction (MI) or stroke and HGPS is associated with amplified interferon responses potentially via the cGAS-STING pathway." (PMID 34381828, 2021). "In contrast, myocardial function and survival were improved in myocardial infarct mice when cGAS and STING were absent." (PMID 34906241, 2021). "For example, genetically or pharmacologically blunting the cGAS-STING signaling pathway in mice ameliorates survival and recovery after myocardial infarction (MI)." (PMID 34114603, 2021).
colon cancer (30 papers, 2017 to 2026). "After adjusting for age, sex, and STING expression, increased cGAS expression remained significantly associated with MSI-H colon cancer in a multiple logistic regression model (β = 1.588, SE = ±0.799, p = 0.047)." (PMID 36612217, 2022). "After adjusting for age, sex, and STING expression, increased cGAS expression remained significantly associated with MSI-H colon cancer in the multiple logistic regression model (β = 1.588, SE = ±0.799, p = 0.047)." (PMID 36612217, 2022). "It has been reported that the loss of the cGAS gene promotes the proliferation of colon cancer cells in vivo." (PMID 35563740, 2022). "In a radiotherapy context, efficacy was abrogated in CT26 colon cancer models using cGAS-deficient tumor cells, indicating cancer-cell-intrinsic expression of cGAS is required for the efficacy of IR." (PMID 33238631, 2020). "The increased susceptibility to AOM-induced colon cancer in cGAS-/- mice is possibly not only a result of the defect in dsDNA recognition but might also from gut dysbiosis from cGAS deficiency." (PMID 36142859, 2022). "Daxx promotes DNA damage repair through homologous recombination and inhibits cGAS-STING signal activation, suggesting that Daxx impairs colon cancer chemotherapy by restricting the cGAS-STING signal activation to mediate antitumor immune responses." (PMID 40296918, 2025). "In contrast, analysis of TCGA data in colon cancer confirmed the correlation between expression of cGAS/STING components and PD-L1 expression, suggesting the need to consider both elements for predicting response." (PMID 41007722, 2025). "Analysis of TCGA colon cancer dataset shows a positive correlation between expression of PD-L1 and components of the cGAS/STING pathway, providing clinical support for cGAS/STING signaling in upregulating PD-L1 expression." (PMID 39469633, 2024). "In colon cancer the activation of cGAS/STING pathway upon the treatment with the DNA-damaging agent oxaliplatin induced ICD of tumor cells, followed by cancer cell phagocytosis by DCs and cytotoxic CD8+T-cells anti-tumor response." (PMID 39709435, 2024). "Previous investigations demonstrated that activation of the cyclic GMP-AMP synthase/stimulator of IFN genes (cGAS/STING) pathway in MDSCs was essential for the attraction of monocyte MDSCs in a CCR2-dependent manner in a colon cancer model." (PMID 38771260, 2024). "Analysis of TCGA colon cancer dataset shows a positive correlation between expression of PD-L1 and components of the cGAS/STING pathway, supporting a role for cGAS/STING signaling in upregulating PD-L1 expression in colon cancer patients." (PMID 39469633, 2024). "To examine the clinical relevance of our findings, we determined the relationship between PD-L1 expression and cGAS/STING signaling in human colon cancer by mining RNA-seq data from TCGA colon cancer dataset (TCGA-COAD)." (PMID 39469633, 2024). "We chose the colon cancer cell line HCT-116 as a positive control for cGAS-STING pathway activation." (PMID 37290532, 2023). "Oral administration of probiotic Lactobacillus rhamnosus GG (LGG) augmented the anti-tumor responses to anti-PD-1 in colon cancer model in a cGAS-STING-dependent way." (PMID 37781354, 2023). "In colon cancer cells, SHP2 was indicated to dephosphorylate poly (ADP-ribose) polymerase 1 (PARP-1) and thus to suppress DNA repair while promoting the cGAS-STING activation to elevate the sensitization of chemotherapy in colon cancer cells." (PMID 37781354, 2023). "A significant loss of cGAS and STING expression has been reported in later stages of colon cancer; moreover, it has been demonstrated that cGAS expression is lost in the earlier stages in comparison to STING expression." (PMID 36612217, 2022). "In parallel, a daily intralesional injection of a whole glucan particle (WGP; the beta-glucan extracted from S. cerevisiae) attenuated the growth of subcutaneous tumor using MC38 (murine colon cancer cell line) in cGAS-/- mice." (PMID 36142859, 2022).
colon cancer (continued). "In bivariate analysis, elevated expression of cGAS and STING was positively associated with MSI-H colon cancer (Fisher’s exact test, both p = 0.0203)." (PMID 36612217, 2022). "In the present study, elevated expression of cGAS and STING was positively associated with MSI-H colon cancer." (PMID 36612217, 2022). "Here, 12 weeks of oral administration of S. cerevisiae protected cGAS-/- mice from azoxymethane (AOM)-induced colon cancers, partly through dysbiosis attenuation (fecal microbiome analysis)." (PMID 36142859, 2022). "In bivariate analysis, elevated expression of cGAS and STING in cancer cells was positively associated with MSI-H colon cancer (Fisher’s exact test, both p = 0.0203)." (PMID 36612217, 2022). "In human colon cancer model, cGAS and STING promoter hypomethylation was shown to reduce expression of cGAS and STING." (PMID 29156566, 2017). "This experimental evidence led to the conclusion that lovastatin enhances the sensitivity of colon cancer cells to radiotherapy by intensifying the activation of the cGAS–STING pathway, facilitating the type I IFN signaling and boosting the infiltration and cytotoxicity of CD8+ T cells." (PMID 40355720, 2025). "cGAS can recognize genomic instability and DNA damage, key features in the onset of colon cancer." (PMID 39050748, 2024). "Moreover, analysis of TCGA colon cancer dataset supports a role for cGAS/STING signaling in upregulating PD-L1 expression." (PMID 39469633, 2024). "No upregulation of cGAS was found in more advanced stage tumors, suggesting that although cGAS is upregulated in early-stage colon cancers, the cGAS-mediated immune stimulation might contribute partially to preventing CRC progression." (PMID 39050748, 2024). "Furthermore, the colonic tumors in cGAS KO mice demonstrated an increase in myeloid-derived suppressive cells, Th17 differentiation, and IL-10 production." (PMID 39050748, 2024). "In this study, we evaluated the impact of RC48 on HER2-positive colon cancer cells both in vitro and in vivo and discovered that RC48 was able to significantly suppress HER2-positive colon cancer and enhance the effectiveness of anti-PD-1 therapy by activating the cGAS-STING pathway." (PMID 37620320, 2023). "The agonist lovastatin can enhance the activity of SHP2 and promote the chemotherapeutic effect in colon cancer by activating the cGAS-STING signaling pathway, which could be a better alternative for colon cancer treatment." (PMID 37163421, 2023). "Strategies targeting the cGAS-STING pathway in colon cancers." (PMID 37781354, 2023). "However, others have found that IFN-ß production is independent of cGAS-STING signaling in mismatch-repair-deficient colon cancer cells." (PMID 39001487, 2024). "In summary, AMP@Zn/Mn-MOF offers a nanoplatform with enhanced antitumor effectiveness through activation of the cGAS-STING pathway and ICD, suggesting that enhanced immune checkpoint blockade-based immunotherapy is promising for colon cancer treatment." (PMID 41603131, 2026). "Here we show that 5-FU and oxaliplatin induce DNA damage and activate cGAS/STING signaling leading to elevated expression of IFNβ, ISG15 and CXCL10 in mouse and human colon cancer cells as well as increased intratumoral CD8+ T cells in mice." (PMID 39469633, 2024). "Scientists also found that cGAS-STING pathway promoted tumor progression in lewis lung cancer (LCC), brain tumor, colon tumor, oral cancer, and tongue squamous cell carcinoma." (PMID 35720348, 2022). "Consequently, this evidence suggests that HMGCR inhibition enhances CD8+ T cell infiltration and cytotoxicity through cGAS–STING activation, leading to robust anti-tumor immunity and increased sensitivity of colon cancer cells to radiotherapy." (PMID 40355720, 2025).
colon cancer (continued). "In this study, we show that 5-FU and oxaliplatin induce DNA damage and activate cGAS/STING signaling leading to enhanced expression of interferon (IFN) β, IFN-stimulated genes and inflammatory cytokines in mouse and human colon cancer cells as well as increased intratumoral CD8+ T cells in mice." (PMID 39469633, 2024). "As such, five out of nine cGAS-/- mice developed intestinal lesions, while no mice in other groups demonstrated colon cancers, supporting the vulnerability of cGAS-/- mice against cancer development." (PMID 36142859, 2022). "Indeed, cGAS not only mediates the synthesis of type I interferon through the classical STING signal pathway but also plays a key role independently of STING in the process of liver injury, colon cancer development, and the suppression of genomic instability." (PMID 38114479, 2023). "The toxicity of MMAE as a microtubulin inhibitor in colon cancer was confirmed, but our initial hypothesis about its relationship with the cGAS-STING pathway was not supported by the negative results." (PMID 37620320, 2023). "Although spontaneous colon cancer activation by AOM is frequently used in wildtype (WT) mice, the protocol could not induce cancer in our WT mice and activated only some cGAS-/- mice, possibly due to the difference in the gut microbiota of mice in the different animal facility environments." (PMID 36142859, 2022).
amyotrophic lateral sclerosis (29 papers, 2021 to 2025). Amyotrophic lateral sclerosis (ALS) is a neurodegenerative disease characterized by progressive muscular paralysis reflecting degeneration of motor neurons in the primary motor cortex, corticospinal tracts, brainstem and spinal cord. "Additionally, it has been reported that cytoplasmic accumulation of TDP‐43, associated with amyotrophic lateral sclerosis, leads to mitochondrial DNA release and activation of cGAS‐STING pathway, which promotes excessive inflammatory response and neuronal loss." (PMID 37646198, 2023). "cGAS–STING pathway has been demonstrated to be involved in pathogenic process of various CNS disorders including Huntington’s disease, amyotrophic lateral sclerosis (ALS), Parkinson’s disease, as well as acute brain injuries like stroke." (PMID 38720350, 2024). "Amyotrophic lateral sclerosis (ALS) is a motor neuron disease, and TARDNA‐binding protein 43 (TDP‐43), the major disease‐associated protein, is known to activate the cGAS–STING signaling pathway by triggering mtDNA release into the cytoplasm." (PMID 38525112, 2024). "Following this, the opening of the mPTP causes mtDNA to be released into the cytosol, activates cGAS-STING signaling, which is a central regulatory mechanism in amyotrophic lateral sclerosis (ALS)." (PMID 38152400, 2023). "Noticeably, activation of the cGAS–STING pathway triggered by the abnormal accumulation of dsDNA in the cytoplasm has been demonstrated in multiple diseases including amyotrophic lateral sclerosis, neonatal hypoxic-ischemic encephalopathy, and cerebral ischemia/reperfusion injury." (PMID 35689216, 2022). "Further, cGAS/STING is implicated in the pathology of CNS neurodegenerative diseases, such as AD/ADRD, Parkinson’s disease, and amyotrophic lateral sclerosis, and may thus constitute a “bridge” between metabolic dysfunction and cognitive impairment." (PMID 36248795, 2022). "In amyotrophic lateral sclerosis (ALS), TDP-43 accumulates in the mitochondria of neurons and causes mtDNA release into the cytoplasm via the MPT pore, leading to cGAS-STING activation and the upregulation of NFκB and IFN-I pathways." (PMID 37941028, 2023). "In mice with amyotrophic lateral sclerosis (ALS), accumulated TAR DNA-binding protein 43 in the cytoplasm can lead to mtDNA leakage and thus activate cGAS, ultimately causing upregulation of NF-κB and IFN-1 levels." (PMID 36545321, 2022). "It has also been proposed that cGAS-STING signaling plays a role in neurodegenerative disorders, including Alzheimer’s Disease, PD, Amyotrophic Lateral Sclerosis, Huntington’s disease, and MS." (PMID 40894167, 2025). "Independent of infection, in a model of misfolded mutant Superoxide dismutase (SOD1)-driven amyotrophic lateral sclerosis (ALS), damaged mitochondria-released mtDNA and mt(DNA/RNA) hybrids activated the cGAS-STING and DDX41-STING pathways, respectively." (PMID 39185415, 2024). "Notably, cytoplasmic accumulation of TAR DNA binding protein 43 (TDP-43), a disease hallmark of amyotrophic lateral sclerosis (ALS), can trigger mtDNA release via the MPTP and VDAC1 oligomers to upregulate the NF-κB and cGAS-STING signaling." (PMID 37325622, 2023). "We then discuss the role of cGAS-STING signaling in different neurodegenerative conditions, including tauopathies, Alzheimer’s disease, Parkinson’s disease, and amyotrophic lateral sclerosis, as well as aging and senescence." (PMID 37941028, 2023). "There is accumulating evidence that cGAS activation is involved in neuroinflammatory diseases such as Parkinson’s disease (or at least a subtype of them), Alzheimer’s disease, and amyotrophic lateral sclerosis (ALS)." (PMID 35406723, 2022). "In amyotrophic lateral sclerosis, the critical disease protein TDP-43 promotes the release of mitochondrial dsDNA into the cytosol, which subsequently activates the cGAS/STING pathway and promotes neurodegeneration." (PMID 36248795, 2022).
amyotrophic lateral sclerosis (continued). "mtDNA release and cGAS–STING activation have also been observed in other stress conditions, including in the aging brain of Alzheimer's disease mice, in amyotrophic lateral sclerosis condition followed by inflammatory cytokine secretion and in ischaemic/reperfusion injury." (PMID 39707673, 2024). "Several studies have shown that the cGAS-STING pathway is activated in the brain of aged mice and humans, as well as in mouse models of Alzheimer’s disease (AD), Parkinson’s disease (PD), and amyotrophic lateral sclerosis (ALS)." (PMID 39149145, 2024). "The cGAS-STING-IFN-I axis in the brain has emerged as a significant contributor to the pathogenesis of various neurodegenerative diseases, including AD, Parkinson’s disease, frontotemporal dementia, amyotrophic lateral sclerosis, and Down syndrome." (PMID 38774266, 2024). "In amyotrophic lateral sclerosis (ALS), TDP-43 protein aggregates have been found to disrupt mitochondrial integrity, leading to mtDNA release and subsequent cGAS-STING activation." (PMID 41300248, 2025). "Therefore, targeting the cGAS-MITA/STING pathway can have potential therapeutic benefits in patients with one of several neurodegenerative disorders, including Alzheimer’s disease, Parkinson’s disease, and amyotrophic lateral sclerosis (ALS)." (PMID 37932533, 2023).